PRKAA2 (protein kinase AMP-activated catalytic subunit alpha 2)
Diseases named in the same sentence as PRKAA2 in open-access papers (continued):
Sharing a sentence is not in itself a finding about the gene and the disease.
liver cancer (4 papers, 2016 to 2025). An epithelial or non-epithelial malignant neoplasm that arises from the liver. "Besides, PRKAA2 knockout in liver cancer enhanced tumor inflammation, also associated with the immune microenvironment." (PMID 37521469, 2023). "SMAD2 and SMAD3 correlated with autophagy-related scores (based on ATG12, ATG7, ATG3, ATG5, ATG4B, PIK3C3, PRKAA2, and GABARAPL1) in liver cancer." (PMID 37790613, 2023).
bladder cancer (3 papers, 2020 to 2024). "In bladder cancer, loss of PRKAA2 resulted in increased tumor proliferation and larger xenografts." (PMID 33681194, 2021). "Moreover, in bladder cancer, CAFs-derived miR-146a-5p was demonstrated to foster CSC niche formation and cancer stemness to drive chemoresistance via co-targeting ARID1A and PRKAA2 (also known as AMPKα2)." (PMID 38802766, 2024).
insulinoma (3 papers, 2020 to 2023). "Both transcripts (Prkaa1 and Prkaa2) were enriched in the whole rat islet and particularly abundant in sorted β-cells and non-β-cells compared to insulinoma INS-1E and cells isolated from the hypothalamus." (PMID 32492936, 2020). "Quantitative-RT-PCR analyses of Prkaa1 and Prkaa2 were performed in insulinoma cells and isolated rat islets, as well as FACS-purified rat β- and non β-cells." (PMID 32492936, 2020). "In particular, pancreatic insulinomas (n = 24) showed a higher expression of the autophagic genes BECN1 (p < 0.001), MAP1LC3B (p < 0.001), SQSTM1 (p = 0.008), TFEB (p < 0.001), PRKAA1 (p = 0.038), and PRKAA2 (p = 0.019) compared to NF-pNET (n = 7)." (PMID 36835048, 2023).
non-small cell lung carcinoma (3 papers, 2019 to 2025). A group of at least three distinct histological types of lung cancer, including non-small cell squamous cell carcinoma, adenocarcinoma, and large cell carcinoma. "In non-small cell lung cancer (NSCLC), PRKAA2 enhances tumor growth and suppresses ferroptosis via the SLC7A11/GSH/GPX4 pathway." (PMID 40575157, 2025).
pancreatic cancer (3 papers, 2016 to 2021). "Here we showed that NSD3 silencing (by targeted shRNA) or KO (using CRISPR/Cas9 method) in pancreatic cancer cells potently inhibited H3K36m2 and expression of these oncogenic genes (Prkaa2, Myc, Irgm1, Adam12, and Notch3)." (PMID 34615858, 2021). "Studies have shown that NSD3-dependent genes (Prkaa2, Myc, Irgm1, Adam12, and Notch3) could exert different cancer-promoting functions in pancreatic cancer." (PMID 34615858, 2021).
lung adenocarcinoma (2 papers, 2023). A carcinoma that arises from the lung and is characterized by the presence of malignant glandular epithelial cells. "While the PRKAA2 gene (encoding AMPK-α2) is subject to relatively frequent mis-sense mutations in human cancers, the PRKAA1 gene is rarely mutated but is instead often amplified, especially in lung adenocarcinomas." (PMID 37962491, 2023).
oral cancer (2 papers, 2019 to 2024). "Glycolytic enzymes Aldoa, Hk2, Tpi1, Pgam2, Pfkl, and Pkm2 as well as the PKA-AMPK pathway genes Prkaa2, Pde4a, Pde10a, Ywhag, and Crebbp were downregulated by BRBs during oral cancer chemoprevention." (PMID 31336728, 2019).
alcoholic hepatitis (1 paper, 2023). Acute hepatitis resulting from ingestion of alcohol. "Furthermore, miR-214, which is upregulated in alcoholic hepatitis, increases ferroptosis by activating ferroptosis-driver genes (ACSL4, PRKAA2, and SLC38A1) through AGO2-dependent transcriptional mechanisms." (PMID 37626043, 2023).
astrocytic tumor (1 paper, 2024). A glial tumor of the brain or spinal cord showing astrocytic differentiation. "Our analysis of the mRNA expression patterns of PRKAA1 and PRKAA2, along with their encoded proteins, revealed that their expression increases with the grade of the astrocytic tumor." (PMID 39001398, 2024).
breast tumors (1 paper, 2018). "Furthermore, the expression of both Cab39 (P = 2.734 × 10–14) and Prkaa2 (AMPK catalytic alpha subunit; P = 1.442 × 10–7) is lower in breast tumors of African-Americans compared with whites." (PMID 30165877, 2018).
diabetic kidney disease (1 paper, 2021). Progressive kidney disorder caused by vascular damage to the glomerular capillaries, in patients with diabetes mellitus. "Additionally, a review stated that PRKAA2 genetic variation has a relationship with diabetic kidney disease." (PMID 37551330, 2021).
Fanconi Anaemia (1 paper, 2022). "In addition, the top two enriched KEGG pathways were: 1) the Fanconi Anaemia pathway (represented by ATR, BRIP1, ERCC4, FANCC and POLH) and the FoxO signalling pathway (represented by CREBBP, NLK, PRKAA2, PRKAB1, PTEN and STK11)." (PMID 35768547, 2022).
hepatoblastoma (1 paper, 2025). Hepatoblastoma (HB) is a malignant hepatic tumor and is the most common pediatric liver cancer. "Notably, PRKAA2 expression is significantly elevated in hepatoblastoma (HB), where it acts as an oncogenic factor by promoting cell proliferation and inhibiting ferroptosis." (PMID 40575157, 2025).
hyperlipidemia (1 paper, 2022). "Pediococcus pentococcus PP04 improved HFD-induced hyperlipidemia and oxidative stress by triggering PRKAA2 and the NRF2/CYP2E1 signaling pathway." (PMID 35204118, 2022).
influenza (1 paper, 2025). An acute viral infection of the respiratory tract, occurring in isolated cases, in epidemics, or in pandemics; it is caused by serologically different strains of viruses (influenzaviruses) designated A, B, and C, has a 3-day incubation period, and usually lasts for 3 to 10 days. "Considering the expression of Prkaa1 and Prkaa2 in control Treg cells of influenza-infected lungs, as well as the compromised tissue-protective function of AMPKα1/α2–deficient Treg cells during viral pneumonia, these data suggest that AMPKα1 and AMPKα2 share redundant functions in this context." (PMID 40100289, 2025).
lentivirus infection (1 paper, 2018). Virus diseases caused by the Lentivirus genus. "As a result, the expression of genes encoding AMPKα1 and AMPKα2 (Prkaa1 and Prkaa2, respectively) and total AMPKα in iWAT-SVF cells were significantly reduced and the activation of AMPK signaling by A-769662 was successfully blocked after Cre lentivirus infection." (PMID 29515462, 2018).
lipodystrophy (1 paper, 2023). A congenital or acquired disorder characterized by abnormal loss or redistribution of the adipose tissue in the body. "ACOX1, ALDOB, protein kinase AMP-activated catalytic subunit alpha 2 (PRKAA2), JAK3, and protein tyrosine phosphatase non-receptor type 11 (PTPN11) have been confirmed to be closely related to β-oxidation of fatty acid, lipogenesis, cholesterol metabolism, and lipodystrophy." (PMID 36397714, 2023).
liver fibrosis (1 paper, 2024). "Additionally, the highly expressed genes GRIA3, FABP4, FADS2, and PRKAA2 have been implicated in lipid metabolism and liver fibrosis." (PMID 38263097, 2024).
motor neurons diseases (1 paper, 2014). "In our network, TDP-43 is linked to AMPK subunit PRKAA2 and a functional link between these two proteins has been suggested in pathological conditions showing that activated AMPK adversely affects mutant TDP-43-induced motor neurons diseases." (PMID 24908109, 2014).
psoriasis (1 paper, 2022). An autoimmune condition characterized by red, well-delineated plaques with silvery scales that are usually on the extensor surfaces and scalp. "Besides, based on CIBERSORT analysis, alterations of immune microenvironment in psoriasis cases were possibly associated with PRKAA2, PEBP1, CISD1, and ACSF2." (PMID 36685512, 2022). "In our analysis, it was found that PRKAA2 was closely related to ferroptosis and psoriasis, and metformin stimulated the expression of PRAKK2." (PMID 36685512, 2022). "Among them, PEBP1, PRKAA2 and ACSF2 are associated with ferroptosis and participate in regulating immune microenvironment in psoriasis cases." (PMID 36685512, 2022). "Typically, ABCC5 (p = 0.0012), CISD1 (p= 3.9e−10) and TRIB2 (p < 2.22e−16) levels in psoriasis cases increased compared with healthy samples, whereas NR5A2 (p = 1.8e−13), PEBP1 (p < 2.22e−16) and PRKAA2 (p < 2.22e−16) levels decreased in psoriasis samples." (PMID 36685512, 2022). "Typically, CISD1 (p = 3.9e-10), TRIB2 (p < 2.22e−16), and ABCC5 (p=0.0012) levels among psoriasis cases increased compared with healthy controls, whereas PRKAA2 (p < 2.22e−16), ACSF2 (p = 3e−15), TIMM9 (p= 0.049), PEBP1 (p < 2.22e−16) and NR5A2 (p=1.8e−13) levels decreased among psoriasis cases." (PMID 36685512, 2022).
retinal degeneration (1 paper, 2022). Degeneration of the retina. "Metformin has been shown to slow retinal degeneration in a range of models via stimulation of PRKAA2/AMPKα2 to enhance metabolic function in both the retina and RPE." (PMID 35196199, 2022).
skin cutaneous melanoma (1 paper, 2023). "The SNV frequency of PRKAA2 in skin cutaneous melanoma was 42%." (PMID 37534256, 2023).
triple-negative breast carcinoma (1 paper, 2018). An invasive breast carcinoma which is negative for expression of estrogen receptor (ER), progesterone receptor (PR), and human epidermal growth factor receptor 2 (HER2). "We also found that miR-92a1 expression is upregulated (P = 1.328 × 10–6) while the expression of its target gene, Prkaa2, is downregulated (P = 0.0053) in triple-negative breast cancers compared with triple-positive breast tumors." (PMID 30165877, 2018).
urothelial bladder cancer (1 paper, 2024). "CAF-derived miR-146a-5p can promote stemness and enhance chemoresistance in urothelial bladder cancer via regulating YY1/SVEP1 and ARID1A/PRKAA2 signal pathways." (PMID 38737906, 2024).
viral pneumonia (1 paper, 2025). Inflammation of the lung parenchyma that is caused by a viral infection. "We found that AMPKα1/α2–sufficient Treg cells express both Prkaa1 and Prkaa2 in lymph nodes and the lung during viral pneumonia and that steady-state splenic AMPKα1/α2–deficient Treg cells have downregulated expression of genes activated during influenza A virus infection." (PMID 40100289, 2025).
tumor (52 papers, 2016 to 2025). "Pseudotime and trajectory analyses showed that CD8+ T cells tended to be exhausted during tumor progression, which was associated with high expression of PRKAA2." (PMID 38424484, 2024). "The obtained expression patterns of PRKAA1 and PRKAA2 mRNA, along with the proteins that they encode, indicate the induction of hypoxia in the tumor microenvironment." (PMID 39001398, 2024). "The pathway-based analysis further revealed that four tumor suppressor genes (Per2, Prkaa2, Npas2, Arntl) were associated with circadian rhythm pathway." (PMID 31523185, 2019). "In addition, the association between PRKAA2 expression and T-cell evolution during tumor progression was explored using Pseudotime analysis, and the role of PRKAA2 in metabolic reprogramming was explored using the R “scMetabolis” package." (PMID 38424484, 2024). "Furthermore, PRKAA2 expression was significantly associated with the tumor immune microenvironment." (PMID 38424484, 2024). "By contrast, PRKAA2 is subject to more frequent mutations and, although many might be passenger mutations caused by genomic instability of cancer cells, some may cause a loss of function consistent with the idea that α2 is a tumour suppressor." (PMID 26934201, 2016). "PRKAA2 plays important roles in both tumor initiation and progression, including the regulation of mTOR kinase activity and the maintenance of NADPH levels." (PMID 38424484, 2024). "Tumors with low PRKAA2 expression displayed an immune hot phenotype, characterized by a high abundance of tumor immune cell infiltrates." (PMID 38424484, 2024). "High expression of PRKAA2, which drives metabolic reprogramming and immune escape of tumor cells, contributes to LIHC development." (PMID 38424484, 2024). "PRKAA2 expression was higher in malignant cells from relapsed tumors compared with PRKAA2 expression in malignant cells from primary tumor samples." (PMID 38424484, 2024). "Our findings suggest that PRKAA2 promotes immune escape of tumor cells via CD8+ T-cell depletion and Treg cell generation, eventually leading to tumor progression." (PMID 38424484, 2024). "Conversely, SCP2, ALDH3A2, and PRKAA2 were found to be expressed at lower levels in tumor tissues." (PMID 40271062, 2025). "Altogether, PRKAA2-mediated tumor immune escape may be due to the activation of immune escape mechanisms in malignant cells and the formation of an immunosuppressive tumor microenvironment." (PMID 38424484, 2024). "Blocking PRKAA2 expression may restore antitumor immunity by enhancing the antitumor response of T cells and reshaping the tumor immunosuppressive microenvironment." (PMID 38424484, 2024). "Single-cell transcriptome atlas analysis showed that PRKAA2 contributes to tumor progression." (PMID 38424484, 2024). "In addition, PRKAA2 facilitates immune escape of tumor cells by promoting CD8+ T-cell exhaustion and the formation of CD4+ Treg cells by reshaping the interaction between malignant cells and T cells and driving dynamic changes in T cells in the TME." (PMID 38424484, 2024). "This suggests that AMPK-α2 might be acting as a tumour suppressor in these cancers, so that tumour cells with mutations in PRKAA2 were being selected for." (PMID 37962491, 2023). "The finding of the differentially changed gene PRKAA2 in our study is important for energy sensor functions, which could influence endothelial activation when tumor cells contact with endothelial cells." (PMID 33681194, 2021). "In cancer cells, studies have shown that AMPK could promote epithelial–mesenchymal transition (EMT) by upregulating Twist 1 and thus promote tumor metastasis, and PRKAA2 has been shown to be involved in cell energy metabolism in various cancers." (PMID 33681194, 2021). "Taken together, the adhesion of tumor cells had a significant effect on mRNAs and lncRNAs in the endothelial cells, in which PRKAA2 is a notable changed molecule and miR-124-3p could regulate its expression and function in endothelial cells." (PMID 33681194, 2021).
tumor (continued). "Our study indicate that PRKAA2 may contribute to LIHC progression by promoting metabolic reprogramming and tumor immune escape through theoretical analysis, which offers a theoretical foundation for developing PRKAA2-based strategies for personalized LIHC treatment." (PMID 38424484, 2024). "Therefore, PRKAA2 emerges as a promising target for novel therapeutic approaches and may also impact tumor immunity in certain cancer types." (PMID 39001398, 2024). "Gene set variation analysis (GSVA) revealed that signaling pathways associated with tumor progression, including PI3K/Akt/mTOR signaling, Notch signaling, angiogenesis signaling, and epithelial–mesenchymal transition (EMT), were significantly enriched in malignant cells with high PRKAA2 expression." (PMID 38424484, 2024). "However, the underlying mechanism by which PRKAA2 regulates glycolysis and tumor growth has not been explored." (PMID 37190158, 2023). "Therefore, we deduced that it is possible there are several lncRNAs in endothelial cells could regulate the “miR-124-3p/PRKAA2” axis in endothelial cells when it is adhered by tumor cells." (PMID 33681194, 2021). "Its downregulation has been shown to result in the inhibition of tumor growth in mouse CRC models, which occurs through upregulation of the PRKAA2 gene—an AMPK subunit." (PMID 40806335, 2025). "The genes EZH2 was significantly higher expressed in tumor tissue while SCP2, ALDH3A2, and PRKAA2 were significantly upregulated in normal tissue." (PMID 40271062, 2025). "Thus, PRKAA2 may promote tumor progression by contributing to CD8+ T-cell exhaustion." (PMID 38424484, 2024). "PRKAA2 was strongly positive in most renal tissues (highly positive in renal tubular cells), according to HPA044540 staining, but weakly positive in most tumor tissues." (PMID 37056387, 2023). "Cell trajectories showed that the expression of PRKCD, PRKAA2, CDK5, and CDK1 genes increased from hepatocytes to tumor cells." (PMID 36120466, 2022). "Compared with the corresponding normal tissue, the qRT-PCR ultimately confirmed the upregulation of SFN, PRKAA2, PITX2, and CDK1 in tumor tissue." (PMID 35592706, 2022). "We found that PRKCD, PRKAA2, CDK5, and CDK1 genes were increased in the progression from hepatocytes to tumor cells." (PMID 36120466, 2022). "The protein levels of PRKAA2, SFN, and CDK1 were upregulated in tumor tissue on the basis of the Human Protein Atlas (HPA) database." (PMID 35592706, 2022). "We then examined the expression of 9 model genes in single cells and found that CDK1, AURKB, CCNA2, and CHEK1 are mainly expressed in CD4 cells, while PRKAA2, CDK5, and PRKCD are mainly expressed in tumor cells." (PMID 36120466, 2022). "Strikingly, all three kinases (i.e. PRKAA1, PRKAA2, and EEF2K) regulating cell metabolism were found to contribute to HGG cell viability, providing a novel tumor vulnerability." (PMID 31420543, 2019). "PRKAA2 may contribute to LIHC progression by inducing metabolic reprogramming of malignant cells and promoting immune escape of tumor cells." (PMID 38424484, 2024). "CDK1, PITX2, PRKAA2, and SFN were all upregulated in the tumor tissue of clinical samples." (PMID 35592706, 2022). "According to the changes of the expression status of differential molecules between the two networks, we identified the top 10 differential mRNAs (PRKAA2, NLGN4X, ST6GALNAC3, DGAT1, TRIB1, GRPR, and MLLT11) and lncRNAs (n339695, n378130, and n410438) in the tumor–endothelium interaction." (PMID 33681194, 2021). "Although the proportion of the cancer mutations in PRKAA2 that cause loss-of-function is not yet clear, the occurrence of frequent mutations suggests that, if anything, AMPK-α2 is acting as a tumour suppressor." (PMID 33375416, 2020).
tumor (continued). "Spearman correlation analysis supported these associations, showing positive correlations between risk scores and tumor stage, grade, invasion percentage, and expression of RAB10, PRKAA2, and LMO3, and negative correlations with BMI, survival time, and LMLN expression." (PMID 40804485, 2025). "ATP5G3, PHKG2 and PRKAA2 may be highly expressed in tumor cells, but the difference was not statistically significant (cor > 0, P > 0.05)." (PMID 34170849, 2021). "Although the genes in (PRKAA2, GNG7, MYL3, NOS1, ADCY1, PLCB1, MYLK3, and MYLK4) the apelin/APJ signaling axis are found to be downregulated and might not be considered responsible in cdRCC progression, downregulation of GNG7 tells a different story due to its tumor‐suppressive activity." (PMID 40304310, 2025).